RWDD2A (RWD domain containing 2A)
Synonyms: RWDD2; MGC13523; dJ747H23.2
Tractability: PROTAC: ubiquitination databases record sites on it.
Gene: Protein-coding gene on chromosome 6 (83,193,337 to 83,198,935, forward strand). Ensembl gene ENSG00000013392.
Subcellular location (Human Protein Atlas): Vesicles
Gene Ontology:
Molecular function: protein binding
Genetic constraint (gnomAD): Loss-of-function variants: 16 observed, 24.57 expected, observed/expected ratio (o/e) 0.65, 90% interval 0.44 to 0.99. The upper end of that interval is the gene's LOEUF score, 0.99, which puts it in group 4 of 6, group 1 being the genes least tolerant of losing a copy. Missense variants: 310 observed, 360.89 expected, observed/expected ratio (o/e) 0.86, 90% interval 0.78 to 0.94. Synonymous variants: 103 observed, 130.17 expected, observed/expected ratio (o/e) 0.79, 90% interval 0.67 to 0.93.
Homologues: Orthologues: chimpanzee RWDD2A (100% identical), macaque RWDD2A (99% identical), dog RWDD2A (98% identical), pig RWDD2A (97% identical), rabbit RWDD2A (96% identical), guinea pig RWDD2A (93% identical), mouse Rwdd2a (93% identical), rat Rwdd2a (93% identical), tropical clawed frog rwdd2a (62% identical), Drosophila melanogaster CG30338 (28% identical). Paralogues in human: RWDD2B (34% identical).
Diseases named in the same sentence as RWDD2A in open-access papers:
RWDD2A is named in the same sentence as 4 diseases in open-access papers, as found by Europe PMC text mining. Sharing a sentence is not in itself a finding about the gene and the disease. The quoted sentences say what the papers report.
male infertility (1 paper, 2023). The inability of the male to effect fertilization of an ovum after a specified period of unprotected intercourse. "We demonstrate our analyses’ potential to identify novel highly germ cell–specific markers (TSPY4 and LUZP4 for spermatogonia; HMGB4 for round spermatids) and identified putatively misregulated genes in male infertility (RWDD2A, CCDC183, CNNM1, SERF1B)." (PMID 36446526, 2023).
RWDD2A also shares sentences with these, for which no sentence is quoted: glioma (1 paper); Infertility (1); Obesity (1).